ARHGEF15 (Rho guanine nucleotide exchange factor 15)
Description:
Guanine nucleotide exchange factor (GEF) that activates RhoA, playing a role in the regulation of actin cytoskeleton organization. Is involved in the regulation of vascular smooth muscle contractility. Additionally, it negatively regulates excitatory synapse development by suppressing the synapse-promoting activity of EPHB2 (By similarity). Does not activate RAC1 or CDC42.
Synonyms: E5; KIAA0915; Vsm-RhoGEF; ARGEF15; FLJ13791; MGC44868; BSVD5; Ephexin5
Tractability: Antibody: the Human Protein Atlas places it where antibodies can reach. PROTAC: UniProt records ubiquitination sites on it.
Gene: Protein-coding gene on chromosome 17 (8,310,241 to 8,323,127, forward strand). Ensembl gene ENSG00000198844.
Subcellular location: Cell projection, dendrite
Subcellular location (Human Protein Atlas): Plasma membrane
Pathways (Reactome):
Signal Transduction: CDC42 GTPase cycle; G alpha (12/13) signalling events; NRAGE signals death through JNK; RAC1 GTPase cycle; RHOA GTPase cycle
Gene Ontology:
Molecular function: guanyl-nucleotide exchange factor activity; protein binding
Biological process: positive regulation of Rho protein signal transduction; regulation of actin cytoskeleton organization; negative regulation of synapse maturation; positive regulation of stress fiber assembly; regulation of small GTPase mediated signal transduction; regulation of postsynapse assembly
Cellular component: plasma membrane; cytoplasm; cytosol; dendrite; glutamatergic synapse; postsynapse
Genetic constraint (gnomAD): Loss-of-function variants: 58 observed, 78.74 expected, observed/expected ratio (o/e) 0.74, 90% interval 0.6 to 0.92. The upper end of that interval is the gene's LOEUF score, 0.92, which puts it in group 3 of 6, group 1 being the genes least tolerant of losing a copy. Missense variants: 1,011 observed, 1,097 expected, observed/expected ratio (o/e) 0.92, 90% interval 0.87 to 0.97. Synonymous variants: 442 observed, 450.51 expected, observed/expected ratio (o/e) 0.98, 90% interval 0.91 to 1.06.
Homologues: Orthologues: chimpanzee ARHGEF15 (99% identical), macaque ARHGEF15 (97% identical), dog ARHGEF15 (89% identical), rabbit ARHGEF15 (88% identical), rat Arhgef15 (86% identical), guinea pig ARHGEF15 (86% identical), mouse Arhgef15 (85% identical), pig ARHGEF15 (74% identical), zebrafish arhgef15b (35% identical), zebrafish arhgef15a (31% identical), Caenorhabditis elegans ephx-1 (26% identical). Paralogues in human: ARHGEF5 (26% identical), ARHGEF19 (24% identical), NGEF (24% identical), ARHGEF26 (22% identical), ARHGEF16 (21% identical), ARHGEF35 (7% identical).
Diseases named in the same sentence as ARHGEF15 in open-access papers:
ARHGEF15 is named in the same sentence as 50 diseases in open-access papers, as found by Europe PMC text mining. Sharing a sentence is not in itself a finding about the gene and the disease. The quoted sentences say what the papers report.
epilepsy (3 papers, 2018 to 2019). A brain disorder characterized by episodes of abnormally increased neuronal discharge resulting in transient episodes of sensory or motor neurological dysfunction, or psychic dysfunction. "Four patients with RE carried CNVs that disrupted genes known to cause other epilepsies; KCTD7, ARHGEF4, ARHGEF15 and CACNA2D1, expanding the phenotypes associated with these genes." (PMID 29789371, 2018). "Five patients with RE carried a rare CNV that disrupted genes associated with other epilepsies (KCTD7, ARHGEF15, CACNA2D1, GRIN2A and ARHGEF4), and 17 cases carried CNVs that disrupted genes associated with other neurological conditions or that are involved in neuronal signalling/development." (PMID 29789371, 2018).
pancreatic cancer (2 papers, 2016 to 2018). "Since higher ARHGEF15 expression levels were associated with a worse prognosis, we attempted to investigate the biological effects of overexpression or knockdown of ARHGEF15 on the cellular phenotype using pancreatic cancer cell lines." (PMID 27145964, 2016). "The effect of gene silencing or overexpression of ARHGEF15 in pancreatic cancer cell lines was examined by introducing siRNAs of ARHGEF15 or the ARHGEF15 expression vector." (PMID 27145964, 2016). "In summary, we found that overexpression of ARHGEF15 in PDAC patients was associated with enhanced growth and motility of pancreatic cancer cells, resulting in a significantly worse prognosis of the patients." (PMID 27145964, 2016). "We showed that upregulation of ARHGEF15 in pancreatic cancer increased activation of the Rho-family proteins, especially RhoA, Cdc42 and Rac, resulting in enhanced motility of the pancreatic cancer cells." (PMID 27145964, 2016). "We initially assessed the ARHGEF15 expression levels in 11 pancreatic cancer cell lines by real-time RT-PCR analysis." (PMID 27145964, 2016). "We also found that the depletion of ARHGEF15 by RNA interference in pancreatic cancer cell lines downregulated the activities of molecules of the Rho signaling pathway, including RhoA, Cdc42 and Rac1." (PMID 27145964, 2016). "Varied expression levels were observed in the cell lines, with a maximum difference in the ARHGEF15 expression level of approximately 86-fold among the pancreatic cancer cell line panel." (PMID 27145964, 2016). "Then, we also showed that ARHGEF15 silencing significantly reduced the motility and viability of the cells, while its overexpression resulted in the development of the opposite phenotype in multiple pancreatic cancer cell lines." (PMID 27145964, 2016). "In addition to the reduced cellular motility mediated by suppression of Rho signaling observed upon gene silencing of ARHGEF15, we found, unexpectedly, that ARHGEF15 also promoted the proliferation of the pancreatic cancer cells." (PMID 27145964, 2016). "We next examined whether modulation of ARHGEF15 expression affected the proliferation of pancreatic cancer cell lines, using Cell Counting Kit-8, a colorimetric modified MTT assay kit." (PMID 27145964, 2016). "Therefore, we examined whether activation of the Rho-family proteins by ARHGEF15 affected the aggressiveness of the pancreatic cancer." (PMID 27145964, 2016). "Since ARHGEF15 is a specific GEF for the Rho-family proteins that is involved in multiple cancer signaling pathways, we further investigated the molecular role of ARHGEF15 in the development of PDAC using pancreatic cancer cell lines." (PMID 27145964, 2016). "miR-193a accelerated pancreatic cancer cell cycle and stimulated cell proliferation and repopulation through inhibiting TGF-β2/TGF-βRIII/SMADs/E2F6/c-Myc signaling, and even destroyed normal intercellular junctions and promoted metastasis via repressing TGF-β2/TGF-βRIII/ARHGEF15/ABL2 pathway." (PMID 29433538, 2018).
bipolar disorder (1 paper, 2022). A disorder of the brain that causes unusual shifts in mood, energy, activity levels and the ability to carry out day-to-day tasks. "In line with this, genetic variation within ARHGEF15 has been associated with hematocrit, red blood cell count, and hemoglobin concentration, but also with psychiatric traits, such as neuroticism and worries as well as bipolar disorder." (PMID 35523767, 2022).
dementia (1 paper, 2025). Loss of intellectual abilities interfering with an individual's social and occupational functions. "Also, there is a relative dearth of published evidence to foster a more detailed examination of the role of PTH and ARHGEF15 mutation in the association between osteoporosis and dementia pathophysiology." (PMID 40700291, 2025). "However, VaD accounts for 15–20% of dementia cases only, and ARHGEF15 mutations do not explain the relationship between more prevalent types of dementia and osteoporosis." (PMID 40700291, 2025).
Hypertension (1 paper, 2022). The presence of chronic increased pressure in the systemic arterial system. "ARHGEF15 encodes a specific guanine nucleotide exchange factor for the activation of Ras homolog family member A (RhoA), a GTPase, which has been linked to higher blood pressure and hypertension over the Rho/ROCK signaling cascade." (PMID 35523767, 2022).
Insulin resistance (1 paper, 2019). Increased resistance towards insulin, that is, diminished effectiveness of insulin in reducing blood glucose levels. "Corticotropin releasing hormone binding protein (CRHBP), ARHGEF15, MME, MAP1A, FGF13, and SHANK3 are novel biomarkers for the development of insulin resistance." (PMID 30678306, 2019).
Iron deficiency (1 paper, 2019). "Iron deficiency altered methylation at the genes regulating ephrin B signaling/ephrin receptor signaling (data not shown), including increased methylation at Ephb1, Itsn1, Prkar1b, and Srgap2, and decreased methylation at Arhgef15, Mknk1, and Slit3 loci." (PMID 31137889, 2019).
lymph node metastasis (1 paper, 2022). "The results suggest that the expression of ECM2, PCDH12, EPAS1, CD93, DLL4, and ARHGEF15 are significantly different in age, N (lymph node metastasis status), and whether radiotherapy is received or not." (PMID 35953532, 2022).
cancer (40 papers, 2010 to 2025). A tumor composed of atypical neoplastic, often pleomorphic cells that invade other tissues. "In accordance with the observation found in association with ARHGEF15 depletion, both the RhoA inhibitor and RhoA gene silencing reduced the proliferative activity, migration and invasiveness of the cancer cells." (PMID 27145964, 2016). "On the other hand, miR-193a destroyed normal intercellular junctions through repressing TGF-β2/TGF-βRIII/ARHGEF15/ABL2 signaling, and caused the repopulated cancer cells to deviate from the primary sites and migrate for metastasis." (PMID 29433538, 2018).
tumor (40 papers, 2005 to 2025). "The results of the upregulation and downregulation experiments led us to infer that ARHGEF15 overexpression in the tumor contributes to the aggressiveness of PDAC." (PMID 27145964, 2016). "The effects of selective ARHGEF15 inhibition and also of ARHGEF15 inhibition on other tumor types remain to be determined in future studies." (PMID 27145964, 2016). "Further, we detected relatively lower expression of TGF-β2, TGF-βRIII, ARHGEF15 and ABL2 in both SW1990- and PANC-1-reporter cells co-cultured with irradiated feeder cells than those with untreated ones in vitro, and similarly in irradiated tumor tissues than in the untreated ones in vivo." (PMID 29433538, 2018). "Our findings in this study suggest that ARHGEF15 could serve as a novel target for the treatment of PDAC, especially benefiting the subpopulation of patients showing overexpression of ARHGEF15 in the tumor cells." (PMID 27145964, 2016).
ARHGEF15 also shares sentences with these, for which no sentence is quoted: cervical carcinoma (21 papers); infection (14); bladder tumors (4); viral infection (4); Alzheimer disease (3); bladder cancer (2); breast carcinoma (2); cervical dysplasia (2); cervical neoplasms (2); head and neck cancer (2); head and neck squamous cell carcinoma (2); leukemia (2); squamous cell carcinoma (2); adenocarcinoma (1); anal carcinoma (1); anal disease (1); Angelman syndrome (1); Bladder (1); breast tumor (1); cerebral small vessel disease (1); cervical disease (1); colorectal cancer (1); colorectal tumors (1); conjunctival squamous cell carcinoma (1); ductal carcinoma in situ (1); dysplasia (1); hemangioma (1); invasive ductal carcinoma (1); kidney cancer (1); latent infections (1).
A further 10 diseases each share a sentence with ARHGEF15 in 1 paper.